RNU6-6P (RNA, U6 small nuclear 6, pseudogene)
Synonyms: U6-6; RNU6-6; RNU6B
Gene: Small nuclear RNA gene on chromosome 10 (13,217,269 to 13,217,375, forward strand). Ensembl gene ENSG00000272055.
Homologues: Orthologues: mouse Gm24486 (100% identical), rat U6 (100% identical). Paralogues in human: RNU6-1 (100% identical), RNU6-2 (100% identical), RNU6-3P (100% identical), RNU6-4P (100% identical), RNU6-5P (100% identical), RNU6-9 (100% identical), RNU6-12P (99% identical), RNU6-13P (99% identical), RNU6-17P (99% identical), RNU6-18P (99% identical), RNU6-25P (99% identical), RNU6-32P (99% identical), and 1288 more.